BCL2 (BCL2 apoptosis regulator)
Diseases named in the same sentence as BCL2 in open-access papers (continued):
Sharing a sentence is not in itself a finding about the gene and the disease.
colon carcinoma (418 papers, 1998 to 2026). "In contrast, overexpression of ganglioside sialidase (Neu3) in colon carcinoma cells was associated with increased Bcl-2 and decreased caspase expression, which is another example of apoptosis suppression associated with GSLs metabolism." (PMID 38254878, 2024). "The results revealed that B. bifidum H3-R2 in combination with L. lactis KLDS4.0325 caused apoptosis in colon cancer cells by increasing caspase-3 and caspase-9 protein levels, enhancing Bax expression, and lowering Bcl-2 expression." (PMID 39410090, 2024). "They concluded that increased expression of miR-125a is associated with decreased expression of BCL-2, in colon cancer cells." (PMID 33430952, 2021). "The miR-21 loss reduced STAT3 and BCL-2 activation, causing an increase in the apoptosis of tumor cells in colitis-associated colon cancer mice." (PMID 32731413, 2020). "Inhibition of the anti-apoptotic proteins favors tumor growth suppression, as Bcl-2 inhibition sensitizes colon cancer cells to death, and mice deficient in Bcl-xL have reduced intestinal tumor burden." (PMID 28977986, 2017). "Besides, the pivotal role of Bcl-2 in autophagy modulation has been examined in colon carcinoma, where the loss of the BH4 domain of the Bcl-2 protein did not influence tumorigenicity in the HT29 colon carcinoma cell line." (PMID 38170401, 2024). "Similarly, in a colon cancer (HT-29) xenograft mouse model, it was reported that PS caused a decrease in the expression of the antiapoptotic Bcl-2 gene at the mRNA level and increased the expression of the proapoptotic Bax, Bak, Bad, and Bid genes." (PMID 39474042, 2024). "The potential mechanisms underlying Nrf3’s promotion of colon cancer cell survival may be associated with the Akt/Bcl-2 pathway." (PMID 38027228, 2023). "Interestingly, the transcription factor SLUG is targeted by FAM3B to promote epithelium mesenchymal transition (EMT) in colon carcinoma cells and inhibition of FAM3B by RNAi is associated to decreased Bcl-2 in colon tumor cells." (PMID 29357840, 2018). "Because BCL-2 inhibition impedes the process of adenoma formation, pharmacological inhibition could play a role as preventive strategy against the development of colon carcinomas in populations that are at high risk for developing this disease." (PMID 26956214, 2016). "Recently, we evaluated uL3 clinical significance in colon cancer and demonstrated that uL3 expression in colon tumor tissues is downregulated; in particular, the decrease in uL3 mRNA levels associated with malignance progression and tumor grade and were inversely proportional to the ratio Bcl-2/Bax." (PMID 33374288, 2020).
colon carcinoma (continued). "Expression levels of Pcna, Ccnd1(CyclinD1), Bcl2, Itga2, Itgb1, Fak, Pik3r1, Akt1, Mtor and Myc were remarkably upregulated and Bax was downregulated in colonic tumors of mice treated with S. moorei." (PMID 39990665, 2025). "In colon cancer and uterine leiomyoma, it promotes apoptosis through Bcl-2 protein expression and increases Bax protein expression." (PMID 40490812, 2025). "In human studies, Campylobacter jejuni infection of HT-29 human colon cancer cells significantly upregulates pro-apoptotic proteins Bax and Bid, downregulates anti-apoptotic protein Bcl-2, and reduces the expression of the goblet cell marker MUC2." (PMID 40969431, 2025). "In line with findings from the literature, our results showed a dose-dependent reduction in BCL-2 protein levels in colon cancer cells." (PMID 41141929, 2025). "Studies have reported that diosmetin decreases Bcl‐2 expression while increasing Bax and Bak expression in liver, lung, breast, gliomas, and colon cancers." (PMID 40666823, 2025). "In silico docking confirmed the anti-colon cancer effect by demonstrating the credible interaction between the active compound and Bcl-2 protein, a key protein that prevents apoptosis." (PMID 40508113, 2025). "In the same study, scientists showed that GO upregulated the expression of the proapoptotic Bax and cleaved the expression of caspase-3 and decreased the expression of the antiapoptotic protein Bcl-2 in colon cancer cells." (PMID 41227361, 2025). "Upregulation of miR-192–5p has also been found to play a role in inhibiting metastatic potential of colon cancer by downregulating expression of Bcl-2, Zeb2 and VEGFA, factors that inhibit apoptosis and promote cell growth." (PMID 40777372, 2025). "The team used HCT AKO, a human colon cancer epithelial cell line deprived of all essential proapoptotic and antiapoptotic Bcl-2 family members, including Bcl-2, Bcl-xL, Bid, Bax, and Bak, through gene knockout." (PMID 40141030, 2025). "Resveratrol derived from grapes modulates the Bcl-2/Bax ratio and enhances caspase activation in colon cancer." (PMID 40283879, 2025). "Expression data from the oncoDB database indicate that the expression of BAX is up-regulated in colon cancer (n = 308) compared to normal tissues (n = 41), whereas the expression of Bcl-2 is down-regulated." (PMID 41180483, 2025). "The dose-dependent treatment of delphinidin in human colon cancer downregulated BCL2, inducing apoptosis and thus reducing cell viability." (PMID 40427676, 2025). "The protein detection results showed that the expression level of antiapoptotic protein Bcl-2, which plays an important role in the mitochondrial apoptosis signaling pathway, was high in colon cancer cells." (PMID 40264676, 2025). "To explore the mechanism underlying the therapeutic effect of LBP in colon cancer, we detected PI3K, AKT, Bax, and Bcl-2 expression levels after knocking down PMI." (PMID 38576495, 2024). "They further conclude that under hypoxia, HIF-1α induces miRNA-210 which in turn enhances autophagy and reduces radiosensitivity by downregulating Bcl-2 expression in colon cancer cells." (PMID 37961749, 2024). "Palestine sweet lime EO has been shown to increase the Bax/Bcl-2 protein ratio in colon cancer cells (SW480), activating the endogenous apoptotic pathway." (PMID 39765890, 2024). "Heparin treatment inhibited apoptosis in colon cancer cells, as evidenced by an increase in the antiapoptotic protein Bcl‐2 and a simultaneous decrease in the proapoptotic protein Bax." (PMID 39479720, 2024). "Natural compound oroxylin A can reduce Bcl-2 expression and induce mitochondrial-mediated apoptosis, thus inhibiting colon cancer cell proliferation and migration." (PMID 39763653, 2024).
colon carcinoma (continued). "Molecular docking analysis revealed that the DY-8 peptide exhibited binding affinity with Bcl-2, Bcl-xL, and Mcl-1, suggesting potential utility in combating colon cancer as functional food ingredients." (PMID 38870120, 2024). "Butyrate-mediated differentiation and apoptosis were accompanied by MYB and BCL2 suppression in colon cancers, and BCL2-mediated protection from apoptosis was overcome by butyrate." (PMID 38835346, 2024). "Yu, etc. found that inhibiting mTOR phosphorylation also cut the expression of Bcl-2 protein in animal colon cancer model experiments in vivo and in vitro." (PMID 38015410, 2024). "Glabridin inhibits cancer cell proliferation by downregulating PI3K, AKT, and mTOR, upregulating Bax, caspase-3, and caspase-9, and reducing Bcl-2, inducing colon cancer cell death through the intrinsic apoptosis pathway." (PMID 39723390, 2024). "Previous experiments have shown that cromolyn can suppress tumor growth signals such as BCL-2 and s100P in the animal model of colon cancer induced by dimethylhydrazine." (PMID 38647571, 2024). "Activated Akt can regulate the expression of apoptosis-suppressing genes Bcl-2, caspase-3, caspase-9 and other proteins to mediate apoptosis in colon cancer." (PMID 36971681, 2023). "The data confirmed that BCL2 was the most stable mRNA among the 55 mRNAs and suitable as the reference mRNA for qPCR analyses in human colon cancer cells." (PMID 37705049, 2023). "In this context, colon cancer lines counteract the antitumor effect mediated by PYY by increasing the expression of Bcl-2, which blocks apoptotic mechanisms." (PMID 37373115, 2023). "The elevated level of Nrf2 promotes cell proliferation in colon cancer, induces transcription of anti-apoptotic protein Bcl2 and impaired the expression of p5396,97." (PMID 37336927, 2023). "In the present study, Nrf3 has been demonstrated to play a crucial role in the survival of colon cancer cells under oxidative stress through the activation of the Akt/bcl-2 signaling pathway." (PMID 38027228, 2023). "HCT116 and Caco2 colon cancer lines increased Bcl-2 expression (which blocks apoptosis; its overexpression is associated with drug resistance) and counteracted the antitumor effect mediated by PYY." (PMID 37373115, 2023). "For example, higher levels of BCL2 expression are associated with poor survival of patients with chronic lymphocytic leukemia (CLL) but improved survival of patients with breast and colon cancer." (PMID 38003498, 2023). "Numerous studies have proposed that the Bax/Bcl-2 ratio can serve as an important prognostic marker of clinical outcomes for patients with many types of cancers, including colon cancer." (PMID 37064948, 2023). "Withaferin-A also possesses its apoptotic action on human colon cancer cells through inhibition of the Notch-1 signalling pathway and down-regulating pro-survival pathways, such as Akt/NF-κB/Bcl-2 in three colon cancer cell lines (HCT-116, SW-480, and SW-620)." (PMID 37063285, 2023). "The expressions of Bcl-2, Bax, and caspase-3 were modified in colon cancer cells treated with stimulated macrophage supernatants, which indicates an activation of the mitochondrial apoptotic pathway." (PMID 37108599, 2023).
colon carcinoma (continued). "Supernatants from murine macrophages stimulated with HYD and MH led to a significant decrease of Bcl-2 expression in colon cancer cells, resulting in a higher Bax:Bcl-2 ratio." (PMID 37108599, 2023). "In another report, the effect of withaferin A on apoptosis has been observed in three different human colon cancer cells, through modulating the Notch-1 signaling pathway and the downregulation of Akt/NF-κB/Bcl-2." (PMID 37259311, 2023). "An increase in Nrf3 expression in colon cancer cells treated with H2O2 partly reversed Akt/Bcl-2 inhibition, whereas it decreased activation of p38 and JNK." (PMID 38027228, 2023). "In Caco2 colon cancer cells, p38 induced apoptosis through increasing pro-apoptotic Bim expression and inactivating pro-survival Bcl-2 members." (PMID 37373017, 2023). "To further elucidate the pro-apoptotic effect of FTGs on colon cancer cells, we detected the expression of Bax, Bcl-2, and caspase-3, which regulates the process of tumor cell apoptosis." (PMID 38202610, 2023). "Our findings demonstrate that upregulating Nrf3 expression mitigates the inhibition of Akt/bcl-2 by H2O2 in colon cancer." (PMID 38027228, 2023). "Matrine inhibited human colon cancer cells growth and induced apoptosis by regulating the upregulation of apoptosis-related proteins Caspase3, Caspase9 and Bax/Bcl-2 ratio." (PMID 36706149, 2023). "In this study, the cytotoxicity of the Akt inhibitor perifosine and the Bcl‐2/Bcl‐xL inhibitor ABT‐737 was tested in colon cancer HT‐29 and HCT‐116 cells cultured in monolayer or in the form of spheroids." (PMID 36523175, 2023). "Overexpression of the bcl-2 gene was also observed in certain solid tumors such as neoplasms of the colon (90%), gastrointestinal tract (60%), prostate carcinoma (30%), non-small cell lung carcinoma (20%) and melanoma." (PMID 36766867, 2023). "Previous studies have shown that ADA possesses anti-proliferative and pro-apoptotic function in colon carcinoma and hepatoma cell lines by increasing caspase-3 activity by increasing Bax and reducing Bcl2 expression." (PMID 35273495, 2022). "Puerarin has been reported to have a chemopreventive effect on colon cancer HT-29 cells by reducing cell viability, inducing apoptosis, activating Bax and caspase 3, and inhibiting c-Myc and Bcl-2." (PMID 35935578, 2022). "Research has also demonstrated that QR promoted the expression of caspase-3 and increased the BAX/BCL-2 ratio to induce apoptosis in human HT-29 colon cancer cells." (PMID 35479514, 2022). "Our current results firmly support the conclusion that Bcl2 is a preferable reference gene for qPCR assay of gene expression in human colon cancer cells treated with cottonseed molecules and bacterial endotoxin LPS." (PMID 36364387, 2022). "BCL2 mRNA was selected as the internal reference for our qPCR analyses since BCL2 was widely studied and least regulated gene in colon cancer cells." (PMID 35058516, 2022). "The data showed that B-cell lymphoma 2 (Bcl2) mRNA was the most stable among the 55 mRNAs analyzed in the human colon cancer cells." (PMID 36364387, 2022). "A previous study analyzed the effect of gossypol on gene expression in human colon cancer cells, using Bcl2 as the reference gene." (PMID 36364387, 2022). "We found that DET mediated the steady and dramatic inhibition of Bcl2 expression at the mRNA level and protein level in the process of elucidating the apoptosis of colon cancer cells induced by DET." (PMID 35563442, 2022). "The data showed that B-cell lymphoma 2 (Bcl2) mRNA was the most stable among the 55 mRNAs analyzed in human colon cancer cells." (PMID 36364387, 2022).
colon carcinoma (continued). "This compound induced apoptosis in HT-29 human colon cancer cells by suppressing BCL-2 and activating caspase-3 protein expression, implying its potential as a colon cancer preventive agent." (PMID 35846992, 2022). "Further, we verified that DET and HA14–1 (Bcl2-specific inhibitor) exhibited synergistic curative effects on colon cancer cells by Jin’s formula (q value ≥ 1.15)." (PMID 35563442, 2022). "In conclusion, this study identified Bcl2 as a preferable reference gene for qPCR assays in human colon cancer cells treated with cottonseed-derived gossypol and bioactive extracts as well as LPS." (PMID 36364387, 2022). "All of the data support the conclusion that Bcl2 is a preferable reference gene for qPCR assay of gene expression in human colon cancer cells." (PMID 36364387, 2022). "A previous study confirmed that miR-365 is downregulated in colon cancer tissues, is involved in tumor progression, and regulates cancer cell behavior by targeting cyclin D1 and Bcl-2." (PMID 35682793, 2022). "Our work suggested that miR-205, which directly interacts with Bcl2, is upregulated in colon cancer cells upon DET treatment." (PMID 35563442, 2022). "BCL-2 expression was also inhibited by the combination of melatonin and radiotherapy, thus enhancing the sensitivity of colon cancer cells to ionizing radiation and increasing cell death in irradiated sarcoma cells." (PMID 35625825, 2022). "P4 also suppresses colonic carcinoma by Bcl-2 down-regulation and caspase-3 up-regulation, as was shown in SW620 cells." (PMID 34683909, 2021). "Moreover, knockdown of TIMP1 could promote apoptosis of colon cancer cells via BCL2-Associated Agonist Of Cell Death (BAD) mediated phosphoration pathway and suppress the migration and invasion of cancer cells through downregulating Fibronectin and upregulating E-cadherin." (PMID 34670584, 2021). "In agreement with the recent study, MS13 induced apoptosis by suppressing the Bcl-2 level in colon cancer cells." (PMID 34366863, 2021). "Orlando and others reported that L. rhamnosus GG intervention in Caco-2, HT-29, and SW480 colon cancer cell lines upregulated the Bax/Bcl-2 ratio, increasing apoptosis in these cells." (PMID 34992527, 2021). "Chen’s group has found that Lnc_ASNR promotes the reduction of cytoplasmic AUF1 levels and inhibits AUF1-mediated degradation of Bcl-2 mRNA in colon cancer RKO cells, which leads to high expression of Bcl-2 and significantly inhibits cell apoptosis." (PMID 34307360, 2021). "The upregulation of the phosphorylation of Tyr705 in STAT3 is frequently detected in human colon cancers and can induce upregulation of anti-apoptotic protein such as Bcl-2, Bcl-xL, and Mcl1 expressions to prevent apoptosis of tumor cells in multiple tumors." (PMID 34900688, 2021). "In conclusion, we have demonstrated that WHSC1 is highly expressed in colon cancer and that it regulates BCL2 expression and cell apoptosis of CRC." (PMID 33469000, 2021). "The expression of the two well-known reference genes was analyzed in the colon cancer cell line under treatment with various concentration of gossypol using internal reference gene BCL2 selected in this study." (PMID 33723275, 2021). "Here in our study, we firstly reported that WHSC1 and H3K36me2 levels were elevated in human CRC, and WHSC1 inhibited colon cancer cell apoptosis by directly binding to the promoter region of BCL2." (PMID 33469000, 2021). "The addition of MPE reduced the content of both Bcl-2 and Bcl-XL proteins in all three colon cancer cell lines." (PMID 34299603, 2021). "Vismodegib is known to inhibit the replication of colon cancer cells and trigger apoptosis through downregulating Bcl-2 although its effect depends on the cell type." (PMID 34445078, 2021).